BCOR (BCL6 corepressor)
Description:
Transcriptional corepressor. May specifically inhibit gene expression when recruited to promoter regions by sequence-specific DNA-binding proteins such as BCL6 and MLLT3. This repression may be mediated at least in part by histone deacetylase activities which can associate with this corepressor. Involved in the repression of TFAP2A; impairs binding of BCL6 and KDM2B to TFAP2A promoter regions. Via repression of TFAP2A acts as a negative regulator of osteo-dentiogenic capacity in adult stem cells; the function implies inhibition of methylation on histone H3 'Lys-4' (H3K4me3) and 'Lys-36' (H3K36me2).
Synonyms: KIAA1575; FLJ20285; ANOP2; MAA2; MCOPS2
Tractability: Small molecule: a high-quality ligand is known. PROTAC: UniProt records ubiquitination sites on it; ubiquitination databases record sites on it; a small molecule that binds it is known.
Gene: Protein-coding gene on chromosome X (40,049,815 to 40,177,329, reverse strand). Ensembl gene ENSG00000183337.
Subcellular location: Nucleus
Subcellular location (Human Protein Atlas): Nucleoplasm
Gene Ontology:
Molecular function: DNA-binding transcription factor binding; heat shock protein binding; histone deacetylase binding; protein binding; transcription cis-regulatory region binding; transcription corepressor activity; ubiquitin-protein transferase activity; RNA polymerase II transcription regulatory region sequence-specific DNA binding
Biological process: chromatin remodeling; heart development; negative regulation of bone mineralization; negative regulation of DNA-templated transcription; negative regulation of tooth mineralization; negative regulation of transcription by RNA polymerase II; odontogenesis; roof of mouth development; specification of axis polarity; heterochromatin formation
Cellular component: BCOR complex; nucleoplasm; nucleus; chromatin; PRC1 complex
Gene-disease validity (ClinGen):
ClinGen rates the evidence that BCOR causes each of these diseases.
microphthalmia, syndromic 2 (X-linked): Definitive.
Cancer hallmarks: suppression of growth (promotes)
Homologues: Orthologues: chimpanzee BCOR (99% identical), macaque BCOR (97% identical), guinea pig BCOR (92% identical), mouse Bcor (89% identical), rat Bcor (89% identical), rabbit BCOR (88% identical), tropical clawed frog bcor (52% identical), zebrafish bcor (39% identical), Drosophila melanogaster CG14073 (17% identical). Paralogues in human: BCORL1 (23% identical).
Diseases named in the same sentence as BCOR in open-access papers:
BCOR is named in the same sentence as 173 diseases in open-access papers, as found by Europe PMC text mining. Sharing a sentence is not in itself a finding about the gene and the disease. The quoted sentences say what the papers report.
sarcoma (95 papers, 2017 to 2025). A usually aggressive malignant neoplasm of the soft tissue or bone. "Conversely, methylation profiles have been useful in identifying undifferentiated sarcomas with specific transcripts or mutations, such as BCOR-altered undifferentiated sarcomas." (PMID 38178234, 2024). "This same subset of pediatric sarcomas lacks the oncogenic fusion but instead has an internal tandem duplication (ITD) associated with exon 15 of BCOR, the so-called BCOR ITD." (PMID 35242139, 2022). "The discrepancies encountered at cross-validation predominantly occurred between the four methylation classes of conventional chondrosarcoma and between three methylation classes of sarcomas associated with BCOR alterations." (PMID 33479225, 2021). "Further association with mutations of the BCL6 repressor gene BCOR, commonly altered in medulloblastomas, neuroepithelial tumors, and sarcomas, highlights a further avenue for interventional study through its regulation of the SHH pathway." (PMID 28966033, 2017). "These groups have been categorized as the round cell sarcomas associated with fusion forming EWSR1 (non-ETS fusions), the CIC (Capicua Transcriptional Repressor) rearrangement associated sarcomas, and BCOR (BCL-6 transcriptional co-repressor) associated sarcomas." (PMID 38954213, 2025). "Whether this aggressive sarcoma represents a molecular subtype of malignant OFMT or a genetic variant of BCOR-rearranged sarcomas remains to be further verified." (PMID 40705064, 2025). "The primary question is whether these tumors represent malignant OFMTs or a variant of the BCOR-rearranged sarcoma family as an independent neoplasm." (PMID 40705064, 2025). "Of note, the differential diagnosis included BCOR-associated sarcoma based partially on a positive BCOR immunostain, and NTRK-related sarcoma as there was weak, patchy cytoplasmic staining for panTrk as well as moderate to strong diffuse cytoplasmic staining for TrkA." (PMID 32490123, 2020). "BCOR-rearranged sarcomas tend to occur more frequently in bone than in soft tissues, accounting for approximately 4% of round cell sarcomas." (PMID 40948502, 2025). "This case underscores the value of BCOR-rearranged sarcomas to be included in the differential diagnosis of round-cell soft tissue and bone tumors in children." (PMID 40932977, 2025). "BCOR-rearranged sarcoma is characterized by a specific in-frame fusion of the BCOR and CCNB3 genes, its hallmark molecular change." (PMID 40932977, 2025). "CRS mostly needs to be differentiated from ES and other Ewing-like undifferentiated small round cell sarcomas, such as BCOR-rearranged sarcoma." (PMID 41244785, 2025). "BCOR-rearranged sarcoma is a rare mesenchymal tumor and a recognized subtype of undifferentiated small round-cell sarcoma." (PMID 40932977, 2025). "Nonetheless, there have been very few cases of primary BCOR-rearranged sarcoma in Pakistan, and because it mimics the morphology of Ewing sarcoma and osteosarcoma, the diagnosis and treatment of BCOR-rearranged sarcoma can be challenging." (PMID 40932977, 2025). "BCOR negativity in the first two tumors in this study created a challenge in the diagnosis of a BCOR-rearranged sarcoma." (PMID 40705064, 2025). "Primarily, BCOR-rearranged sarcomas were predominantly reported in bones and sporadically found in extraosseous tissues involving the kidney, neck, chest wall, and soft palate, with a preferred morbidity in male adolescents and children." (PMID 40932977, 2025). "This case highlights the importance of considering BCOR-rearranged sarcoma in the differential diagnosis of pediatric bone and soft tissue tumors, as its clinical and radiological features can mimic more common malignancies like osteosarcoma." (PMID 40932977, 2025). "Especially BCOR-rearranged sarcoma patients older than 13 years tend to have better 3-year event free survival (41.2%)." (PMID 39930783, 2025).
sarcoma (continued). "Molecular analysis will also diagnose other rare round cell sarcomas, such as CIC-rearranged and BCOR-altered sarcomas and other newer entities." (PMID 39550489, 2025). "The results revealed that 56% of BCOR-positive sarcomas, 50% of undifferentiated uterine sarcomas, and 33% of spindle cell/sclerosing rhabdomyosarcomas presented moderate-intensity staining ranging from 0 to 56%." (PMID 40548109, 2025). "Another subtype is BCOR-rearranged sarcomas, commonly involving a BCOR-CCNB3 fusion, and they predominantly arise in the bone and soft tissues of adolescents and young adults." (PMID 40932977, 2025). "ZC3H7B::BCOR or, rarely, BCOR::ZC3H7A-rearranged sarcomas are rare, constituting 5% of all BCOR-altered sarcomas." (PMID 40705064, 2025). "CDKN2A/B deletions and correspondingly low levels of CDKN2A mRNA have been reported in high-grade endometrial sarcomas and pediatric sarcomas with BCOR genetic alterations." (PMID 41155410, 2025). "BCOR gene alterations are uncommon genetic drivers reported in sarcomas and high-grade glial neoplasms in pediatric patients and young adults." (PMID 40705064, 2025). "In contrast, NKX2.2 is expressed in ES, and BCOR is expressed in BCOR-rearranged sarcoma, and it can be differentiated from CRS based on EWSR1-FLI1, EWSR1-ERG, BCOR, and the expression of other related genes." (PMID 41244785, 2025). "Histologically, BCOR CCNB3 sarcoma occurs typically as sheets or fascicles of spindle-to-round cells with monomorphic nuclei, subtle chromatin, and minimal cytoplasm." (PMID 40932977, 2025). "Since its discovery in 2012 through RNA sequencing of bone tumors, BCOR-rearranged sarcoma has become the third most common small round cell sarcoma subtype." (PMID 40932977, 2025). "BCL6 corepressor (BCOR)-rearrangement sarcoma, an undifferentiated round cell sarcoma, is rare, and its pathophysiology is diverse." (PMID 40799881, 2025). "Examples of antibodies serving as surrogate markers of sarcoma-specific genetic aberrations, e.g., fusions, amplifications, and point mutations, include SS18-SSX or SSX, TFE3, SMARCB1, BCOR, MDM2, DDIT3, and PAX3." (PMID 40526340, 2025). "Recently, a subgroup of undifferentiated round-cell sarcomas has been genetically identified as BCOR (B-cell Line 6 Corepressor)-altered sarcomas (BAS)." (PMID 38840999, 2024). "This overlaps with Ewing sarcoma, sarcoma with BCOR alteration, mesenchymal chondrosarcoma, and SEF, also in our cohort." (PMID 38332052, 2024). "The most common represented histological subtypes were synovial sarcoma (n=24), undifferentiated sarcoma (n=16), malignant peripheral nerve sheath tumor (MPNST) (n=12), epithelioid sarcoma and sarcoma with BCOR genetic alterations (n=7)." (PMID 39534097, 2024). "The fact that all of the different BCOR-rearranged sarcomas cluster together in gene expression profilings suggests that all involved mutant BCOR proteins have a common mechanism of action." (PMID 38611033, 2024). "The remaining 10/27 MPNSTs variably classified as schwannoma, osteosarcoma, BCOR-altered sarcoma, rhabdomyosarcoma (RMS)-MYOD1 mutant, RMS-like, and embryonal RMS or did not match with any defined entity." (PMID 38178234, 2024). "A core needle biopsy revealed a high-grade sarcoma with positivity for BCOR by immunohistochemistry raising the possibility of a BCOR-altered sarcoma." (PMID 38436779, 2024). "Immunohistochemistry for BCOR and MYOD1 were positive in the two cases classified as BCOR-rearranged sarcoma and MYOD1-mutant RMS, respectively (#11 and #12), thus corroborating the diagnoses suggested by DNAm profiling." (PMID 38178234, 2024). "The differential diagnosis in this case was broad and included malignant peripheral nerve sheath tumor (MPNST), synovial sarcoma, solitary fibrous tumor (SFT) and BCOR-rearranged sarcoma." (PMID 38137051, 2023). "Other “BCOR rearranged sarcomas” have been described with molecular characteristics as BCOR‐ITD (internal tandem duplication)." (PMID 37212486, 2023).
sarcoma (continued). "In this report, we present a unique case of sarcoma with internal tandem duplication of BCOR gene originating in the nasal region." (PMID 38170001, 2023). "Sarcoma with BCOR genetic alteration is an extremely rare form of sarcoma that shares morphological similarities with the Ewing sarcoma." (PMID 38170001, 2023). "The second group shows internal tandem duplication in BCOR (BCOR-ITD sarcomas), described in infantile undifferentiated round cell sarcomas and primitive myxoid mesenchymal tumors of infancy." (PMID 36983010, 2023). "Sarcomas with BCOR genetic alterations are clinically distinct sarcomas arising in soft tissue and bone and divided into two main groups." (PMID 36983010, 2023). "To conclude, we have shared an extraordinary case of sarcoma featuring BCOR-ITD, occurring in a rare site and demonstrating an exceptional response to the standard VDC-IE chemotherapy regimen." (PMID 38170001, 2023). "In contrast, the 29 patients in the “BCOR rearranged sarcoma” group were younger (p < 0.001) with a median age of 0.9 years overall (0.1–19.1) and specifically 4 years (range, 0.1–19.1) for BCOR::CCNB3 (n = 18) and 1 year (0.3–18.3) for BCOR‐ITD (n = 7)." (PMID 37212486, 2023). "Median age of patients at initial diagnosis with “CIC fused sarcoma” was 14 years (range, 0.9–23.8), and 0.9 years (range, 0–19.1) for “BCOR rearranged sarcomas”." (PMID 37212486, 2023). "Overall, the 3 year‐EFS were 44.0% (95% CI 28.7–67.5) and 41.2% (95% CI 25.4–67.0) for “CIC fused sarcoma” and “BCOR rearranged sarcoma” groups, respectively (p = 0.97)." (PMID 37212486, 2023). "The first group is characterized by sarcomas with BCOR-related gene fusions (BCOR-fusion sarcomas), most frequently BCOR::CCNB3." (PMID 36983010, 2023). "After the immunohistochemistry screening, 12/105 cases emerged for the Trk protein expression, including 8/96 Ewing sarcomas, 3/5 USTS and 1/1 sarcoma with BCOR genetic alteration, with a comprehensive percentage of positive immunoreactivity of 11.4%." (PMID 35295613, 2022). "Among these, protein capicua homolog (CIC)- and B-cell lymphoma 6 corepressor (BCOR)-rearranged sarcomas along with sarcomas carrying Ewing sarcoma breakpoint region 1 (EWSR1)-non-erythroblast transformation specific (ETS) fusions feature most prominently." (PMID 36158667, 2022). "BCOR-CCNB3 sarcomas, characterized with a BCOR and CCNB3 fusion gene, are round cell undifferentiated sarcomas that share morphologic and immunohistochemical features with Ewing sarcoma (ES)." (PMID 35875106, 2022). "A diagnosis of relapsed undifferentiated sarcoma was refined to BCOR-sarcoma due to the identification of the BCOR-CCNB3 fusion and absent EWSR1 fusion." (PMID 36182817, 2022). "Genetically and clinically different round cell sarcomas were recently identified: round cell sarcoma with EWSR1-non ETS (NFATC2 and PATZ1 being the most common ones), CIC-rearranged sarcomas and sarcomas with BCOR genetic alteration." (PMID 34514574, 2021). "These include sarcomas with BCOR alterations, CIC-rearranged sarcoma (see ‘WT1 and ETV4’), and round cell sarcoma with EWSR1-non-ETS fusions." (PMID 33921435, 2021). "A recent study reported BCOR (Bcl6 interacting co-repressor) overexpression in SFT compared with other types of sarcoma." (PMID 34680383, 2021). "BCOR-rearranged sarcomas have a round-cell or spindle-cell morphology with a prominent myxoid stroma." (PMID 34722090, 2021). "Differential diagnoses of extraskeletal ES include alveolar RMS, poorly differentiated synovial sarcoma, DSRCT, CIC-rearranged sarcoma, and sarcoma with BCOR genetic alterations." (PMID 32867125, 2020). "Cluster C1 contained all the BCOR-rearranged sarcomas, and four samples carried a YWHAE-NUTM2 fusion (two ESS and two from the control cohort)." (PMID 32933053, 2020). "It was initially signed out descriptively as undifferentiated spindle cell sarcoma, with differential diagnosis including BCOR-associated sarcoma and NTRK-related sarcoma." (PMID 32490123, 2020).
sarcoma (continued). "While outcomes in patients with BCOR-altered sarcoma are comparable with those in Ewing sarcoma, survival with CIC-rearranged sarcoma is poor irrespective of chemotherapy; use of soft tissue sarcoma regimens such doxorubicin and ifosfamide have similar outcomes for those with localised disease." (PMID 39550489, 2025). "Fluorescence in situ hybridization (FISH) studies for EWSR1 gene rearrangement or whole transcriptome exome sequencing can help assist in excluding an EWSR1-rearranged sarcoma, round cell sarcomas with BCOR alterations, and small round cell sarcomas, NOS, respectively." (PMID 40599504, 2025). "Notably, capillary-sized blood vessels were present throughout the tumor, which made BCOR-rearranged sarcomas, myxoid liposarcoma with small cell morphology, and GLI1-altered soft tissue tumors the main differential diagnoses." (PMID 40791569, 2025). "As a result, tumors with distinct molecular drivers—such as CIC-rearranged sarcoma or BCOR-rearranged sarcomas—may be clumped under broader morphological categories such as sarcoma with small round cell features." (PMID 40427203, 2025). "Nine fusion genes were specific to particular histotypes, including SYT::SSX fusion in synovial sarcoma, EWSR1::FLI1 fusion in ES, EWSR1::NR4A3 fusion in EMC, BCOR::CCNB3 fusion in sarcoma with BCOR genetic alterations, and EWSR1::CREB3L1 fusion in sclerosing epithelioid fibrosarcoma." (PMID 40755265, 2025). "Currently, it remains controversial whether ZC3H7A/B::BCOR-positive sarcomas constitute another provisional entity of a “fusion-driven” soft tissue sarcoma or a genetic subset/variant in the spectrum of malignant OFMTs or BCOR-rearranged sarcomas." (PMID 40705064, 2025). "Additionally, among the seven cases of sarcoma with BCOR genetic alterations, six patients (85.7%) exhibited high expression of various markers (four for c-kit, six for PDGFRα, and two for VEGFR2)." (PMID 39534097, 2024). "BCL6 corepressor (BCOR) gene alteration is a genetic signature of rare subsets of sarcomas." (PMID 39062853, 2024). "In this study, we report the first case of BCOR-rearranged sarcoma with a novel CLGN fusion that shared morphological and immunophenotypical similarities with other more common fusion variants, which contribute to the continued expanding molecular subtypes of BRS." (PMID 36765856, 2023). "Additionally, SATB2, TLE1, and cyclin D1 expressions are present in most sarcomas with BCOR genetic alterations." (PMID 36983010, 2023). "Sarcoma with BCOR genetic alteration is an exceptionally rare and emerging subtype of sarcoma." (PMID 38170001, 2023). "We reviewed the literature and identified a total of 166 reported cases of BCOR-rearranged sarcoma." (PMID 38170001, 2023). "BCOR-related sarcoma is a primitive round cell sarcoma showing BCOR genetic alterations." (PMID 36941503, 2023). "BCOR-fusion and BCOR-ITD sarcomas show a similar gene expression signature." (PMID 36983010, 2023). "The result of the second IHC panel prompted us to consider a BCOR-rearranged sarcoma." (PMID 36765856, 2023). "Additionally, satisfactory results were obtained after the treatment of a child with a refractory pediatric sarcoma harboring paracentric inversion on the short arm of chromosome X, resulting in the fusion of the BCOR and CCNB3 genes." (PMID 36839989, 2023). "BCL6 corepressor (BCOR) sarcomas are rare and defined by alterations of the BCOR gene." (PMID 35884441, 2022). "In tumors with BCOR gene rearrangements demonstrated sarcomas." (PMID 35242139, 2022). "BCOR-rearranged sarcomas are rare and belong to the Ewing-like sarcomas (ELS)." (PMID 34331570, 2022). "BCOR-rearranged sarcomas arise predominantly in older children and young adults." (PMID 34722090, 2021).